Y_RNA (Y RNA )
Gene: Miscellaneous RNA gene on chromosome 2 (175,176,493 to 175,176,586, reverse strand). Ensembl gene ENSG00000200121.
Homologues: Orthologues: chimpanzee Y_RNA (100% identical), macaque Y_RNA (94% identical). Paralogues in human: Y_RNA (87% identical), RNY4 (84% identical), Y_RNA (84% identical), RNY4P3 (83% identical), Y_RNA (83% identical), RNY4P14 (82% identical), RNY4P6 (82% identical), Y_RNA (82% identical), RNY4P19 (81% identical), RNY4P23 (81% identical), RNY4P34 (81% identical), RNY4P7 (81% identical), and 87 more.